APOE (apolipoprotein E)
Diseases named in the same sentence as APOE in open-access papers (continued):
Sharing a sentence is not in itself a finding about the gene and the disease.
atherosclerosis (continued). "Two studies used a genetic induction model with ApoE −/− mice, making them susceptible to severe hypercholesterolemia and atherosclerosis, while one study employed chemical induction using streptozotocin (STZ)." (PMID 40565686, 2025). "When fed an HFD, the transgenic mice overexpressing the human dysfunctional APOE*3-Leiden variant exhibits an exacerbated susceptibility of hyperlipidemia and atherosclerosis." (PMID 41516253, 2025). "In the absence of epidemiological evidence, assessment of the health effects of a product, chemical or therapy on the progression of atherosclerosis would necessitate long-term animal exposure studies such as the use of the Apolipoprotein E deficient mouse." (PMID 40661062, 2025). "Prdx1 (peroxiredoxin 1) deficiency in MØ leads to increased susceptibility to oxidative stress and impaired clearance of modified LDL due to defective lipophagic flux, thereby promoting atherosclerosis in apoE-deficient mice." (PMID 40607379, 2025). "In contrast, other studies have shown that in ApoE-deficient mice, the depletion of Tc correlated with the regression of atherosclerosis." (PMID 39944697, 2025). "PSRC1 deficiency in ApoE-/- mice accelerated atherosclerosis by boosting TMAO, increased TMA-producing bacteria and plasma betaine and TMAO levels." (PMID 40356907, 2025). "A study investigating the effects of berberine on atherosclerosis in apolipoprotein E‐deficient (ApoE−/−) mice found that berberine enhanced the uptake of modified LDL (DiO‐Ac‐LDL) by inducing macrophage scavenger receptor A (SR‐A) expression." (PMID 40634132, 2025). "One study examined the impact of KYT-1 and KYT-36 (two specific gingipain inhibitors for Rgp and Kgp, respectively) on the development and progression of atherosclerosis in apoE knockout mice, a model genetically predisposed to develop atheroma." (PMID 40839040, 2025). "TNF-α is reported in the edges of the inflammatory lesions, so that atherosclerosis diminished in the apoE-deficient mice with the disrupted TNF-α." (PMID 40823653, 2025). "The ApoE−/− mice are genetically predisposed to developing atherosclerosis, making them a suitable model for studying this cardiovascular disease." (PMID 41142432, 2025). "In this study, we investigated the effect of β-sitosterol on HFD-induced atherosclerosis in ApoE−/− mice and explored the underlying mechanisms involving the MAPK/Nrf2/NLRP3 pathway." (PMID 40966231, 2025). "In a study with Ku80‐deficient atherosclerotic ApoE−/− mice, DNA double‐strand breaks were shown to play a causative role in the induction of a pro‐inflammatory response that precedes the onset of atherosclerosis." (PMID 40279334, 2025). "Supporting these findings, PXR activation induced hypercholesterolemia in WT mice and exacerbated atherosclerosis in ApoE-deficient mice, whereas PXR deficiency reduced atherosclerosis in ApoE-deficient mice." (PMID 40726484, 2025). "Canagliflozin has been demonstrated to reduce the progression of atherosclerosis by attenuating inflammatory processes in diabetic atherosclerosis-prone apolipoprotein E-deficient (ApoE−/−) mice." (PMID 40149704, 2025). "The deletion of IL-1β led to a 33% reduction in total atherosclerotic lesions in high-fat diet (HFD)-fed apolipoprotein E deficient (apoE−/−) mice, demonstrating the effectiveness of anti-inflammatory treatment in improving atherosclerosis." (PMID 40422906, 2025). "The atherosclerotic model of ApoE-deficient mice revealed accelerated progression of atherosclerosis after myocardial infarction." (PMID 41465273, 2025). "GE treatment significantly reduces serum lipids, oxidative stress damage, lipid deposition, and aortic plaque lesions associated with atherosclerosis in HED‐fed ApoE−/− mice." (PMID 40718724, 2025).
atherosclerosis (continued). "In this study, we first explored the potential benefits of leflunomide on atherosclerosis and revealed the underlying mechanism in ApoE-/- mice." (PMID 39113703, 2024). "This study aimed to explore the protective effects of GV1001 against Pg-induced periodontal disease, atherosclerosis, and AD-like conditions in Apolipoprotein (ApoE)-deficient mice." (PMID 38892314, 2024). "KEAP1-R483S mutation also limited the protective effect of MCL on atherosclerosis progress and macrophage ferroptosis in ApoE−/− mice." (PMID 38100883, 2024). "Previous studies in apolipoprotein E knockout mice have shown that SGLT2i is associated with attenuated progression of atherosclerosis." (PMID 39039597, 2024). "It was the balance between ApoB-specific conventional and regulatory T lymphocytes reaching arterial wall that determined susceptibility of apolipoprotein E deficient (ApoE−/−) mice to atherosclerosis." (PMID 39061983, 2024). "ApoE −/− mice are prone to easier development of atherosclerosis and increased susceptibility to vascular endothelial cell dysfunction, raising concerns." (PMID 39424429, 2024). "Verbascoside plays a role in the development of an atherosclerosis model by regulating glycerophospholipid metabolism in the liver of Western diet-fed apolipoprotein E-deficient mice." (PMID 38594761, 2024). "In ApoE−/− mice with atherosclerosis, it was associated with elevated levels of TC, LDL, cholesterol ester (CE), and free cholesterol (FC)." (PMID 39273193, 2024). "Endothelial cell-specific deletion of Pannexin1 (Panx1) in apolipoprotein E-deficient (Apoe-/-) mice increased atherosclerosis, suggesting a protective role for Panx1 channels in arterial endothelial function." (PMID 39775604, 2024). "Atherosclerosis-prone Apolipoprotein E-deficient (Apoe−/−) mice that were fed a diet rich in cholesterol for 10 weeks showed increased LDL buildup and greater apoptosis in the area of the common carotid artery under the thinner EGC." (PMID 38785504, 2024). "Subsequent administration of a miR-27b-3p mimic induced inflammation and atherosclerosis in apolipoprotein E deficient (ApoE−/−) mice, whereas PPARα overexpression counteracted these effects and provided protection against atherosclerosis." (PMID 39327610, 2024). "The role of LOX-1 in promoting atherosclerosis was also investigated in mice that were genetically modified to have endothelial-specific LOX-1 overexpression with an ApoE deficiency background." (PMID 38790688, 2024). "Taurine-formulated VSOPs (VSOP-T) were repeatedly intravenously injected at 100 μmol Fe/kg in apolipoprotein E-deficient (ApoE KO) mice with diet-induced atherosclerosis." (PMID 38727367, 2024). "Our present results concord with our previous findings that PACAP deficiency in ApoE−/− aggravates atherosclerosis, suggesting that endogenous PACAP is atheroprotective." (PMID 39769009, 2024). "Regarding ApoE-deficient mice, which are an established experimental model of atherosclerosis, spatial learning and long-term memory was impaired in the Morris water maze (MWM)." (PMID 38469142, 2024). "T decreased atherosclerosis in female mice generated on an atherosclerosis-prone apoE-deficient background, but increased atherosclerosis in apoE-deficient male mice." (PMID 39225098, 2024). "A. Heduschke and co-authors investigated the effects of GDF-15 on autophagy using an in vitro human atherosclerotic macrophage model and an in vivo GDF-15-deficient (GDF-15−/−) apolipoprotein E knockout (apoE−/−) mouse model of experimental atherosclerosis." (PMID 38396781, 2024). "In ApoE−/− mice, the administration of IL-18 enhances atherosclerosis, whereas a deficiency of IL-18 signaling inhibits the process of atherosclerosis development and stability." (PMID 39685608, 2024). "Mechanistically, APOE has been associated with insulin resistance in the muscles of mouse models, islet amyloidosis, and adipocyte enlargement in atherosclerosis." (PMID 38396891, 2024).
atherosclerosis (continued). "This inhibition contributed to the prevention of atherosclerosis development in ApoE-deficient mice." (PMID 38892314, 2024). "Surprisingly, while being less prone to atherosclerosis than ApoE-deficient mice, these animals have much higher total plasma cholesterol and triglyceride levels when fed a Western-style diet." (PMID 38629090, 2024). "Our previous data also revealed that endothelial cell ferroptosis was observed in estrogen-deficient ApoE−/− female mice, while estrogen supplementation attenuated atherosclerosis by inhibiting endothelial cell ferroptosis." (PMID 38100883, 2024). "Here, we report the following key findings: i) whole-body haploinsufficiency of the insulin receptor in Apolipoprotein E (ApoE) deficient mice leads to accelerated atherosclerosis in the thoracoabdominal aorta and at the level of the aortic sinus." (PMID 39401163, 2024). "ApoE−/− and ApoE−/−/eIF6+/− mice on normal chow diet or a high-fat diet were treated for 16 weeks; eIF6 deficiency was evaluated atherosclerosis." (PMID 39225466, 2024). "Apolipoprotein E (ApoE; the ApoE4 gene is associated with atherosclerosis and Alzheimer’s disease) promotes osteogenesis and decreases osteoclastogenesis, with aged ApoE-KO mice exhibiting severe osteoporosis compared to Wild Type mice." (PMID 39725855, 2024). "For example, overexpression of glutathione peroxidase 4 (GPX4) inhibited atherosclerosis progression in apolipoprotein E-deficient (ApoE-/-) mice." (PMID 39403576, 2024). "To validate our in vitro observations in a disease context, we induced atherosclerosis, a chronic inflammatory vascular disease associated with matrix stiffening, in ApoE KO mice by administering a high-fat diet (HFD) to create a hyperlipidemic condition." (PMID 39403372, 2024). "R568 was also shown to delay the progression of both aortic calcification and atherosclerosis in uremic apolipoprotein E-deficient mice." (PMID 39165274, 2024). "Apolipoprotein E (ApoE)-deficient mice fed a high-fat diet (HFD) were selected to establish an atherosclerosis model." (PMID 38794213, 2024). "Previous research showed that a feed-forward loop involving extracellular matrix deposition and LOX-dependent collagen crosslinking promotes atherosclerosis progression in hyperlipidemic, ApoE-deficient mice." (PMID 39143955, 2024). "ii) Mice haploinsufficient for the IR deficient in ApoE also deficient in Nox2 (IR+/−/ApoE−/−/Nox2−/y) develop accelerated atherosclerosis and disruption of the aortic wall." (PMID 39401163, 2024). "The present study was designed to investigate the effects of ADF on atherosclerosis in apolipoprotein E-deficient (Apoe−/−) mice." (PMID 39872376, 2024). "Dementia-prone APP23 mice mated with atherosclerosis-prone apolipoprotein E-deficient (ApoE-/) mice have larger and more inflammatory aortic atherosclerotic lesions than pure ApoE-/- mice." (PMID 38441007, 2024). "This study aimed to investigate the susceptibility of apoE knockout (KO) rabbits, in comparison with wild-type (WT) rabbits, to diet-induced hyperlipidemia and atherosclerosis." (PMID 39087075, 2024). "To answer this question, we generated atherosclerosis-prone mice with whole-body insulin resistance secondary to haploinsufficiency of the insulin receptor (IR+/−) deficient in ApoE−/− (IR+/−/ApoE−/−)." (PMID 39401163, 2024). "The authors put hamsters on a high-cholesterol/high-fat diet to assessthe association between APOC3 and atherosclerosis and observed reducedlevels of TG, total cholesterol, ApoB, and ApoE and enhancedlevels of HDL-C and ApoA1." (PMID 39228490, 2024).
atherosclerosis (continued). "Treatment with anti- PGF antibody (alphaPlGF mAb) significantly reduced the size of early plaques and inhibited atherosclerosis progression in the ApoE-deficient mice." (PMID 38333413, 2024). "Plasmalogen enrichment via batyl alcohol supplementation attenuated atherosclerosis in ApoE- and ApoE/GPx1-deficient mice." (PMID 39247623, 2024). "In particular, atherosclerosis and nephropathy are the most frequently reported complications associated with APOE genotypes." (PMID 38396891, 2024). "This study aimed to elucidate the pathogenesis of atherosclerosis development using atherosclerosis model mice (ApoE KO mice) and mice deficient in IL-33 receptor ST2 (ApoEST2 DKO mice)." (PMID 38674885, 2024). "Genetic deletion of interleukin-1α reduces ER stress-induced CHOP expression in macrophages and attenuates the progression of atherosclerosis in apoE-deficient mice." (PMID 39742022, 2024). "In this investigation, we aimed to assess the influence of apoE deficiency on hyperlipidemia and atherosclerosis by utilizing apoE KO rabbits as an experimental model." (PMID 39087075, 2024). "In atherosclerosis, genetic deficiency of CBL-b aggravated atherosclerosis in ApoE-/- mice by recruiting CD8+ T cells to plaques." (PMID 39349831, 2024). "Subcutaneous infusion of apolipoprotein B100 (ApoB100) to ApoE−/− mice was associated with abrogated atherosclerosis development and progression of atherosclerosis, which also appeared to be CD4+CD25+ Treg-dependent." (PMID 39061983, 2024). "Both genetic ablation of LXN and BMT with LXN-deficient hematopoietic cells improved atherosclerosis in ApoE-/- mice." (PMID 39424784, 2024). "Future studies will be focused on the multi-facetted role of ApoE and prospective analysis of plasmalogens causal relationship and potential therapeutic implications of the macrophages’ protective profile against atherosclerosis." (PMID 39247623, 2024). "Oral inoculation with P. gingivalis for ApoE‐deficient mice reduced the diversity of gut microbiota, decreasing Firmicutes, increasing Bacteroidetes, and exacerbated atherosclerosis." (PMID 39675010, 2024). "FBN1 variant (C1039G (+/-)) can also promote atherogenesis and a highly unstable plaque phenotype in apolipoprotein E-deficient (ApoE (-/-)) mice model of atherosclerosis." (PMID 38715006, 2024). "The apolipoprotein-E-deficient (apoE−/−) mouse is a pre-clinical model of human atherosclerosis that mimics the human metabolic signature and accumulates aortic atherosclerotic plaque." (PMID 38337615, 2024). "In fact, using an ApoE−/− mouse model of atherosclerosis we have recently shown that PACAP deficiency aggravates atherosclerosis in mice fed standard chow for 30 weeks." (PMID 39769009, 2024). "Conversely, individuals carrying APOE2 have a higher risk of developing atherosclerosis due to the loss of APOE’s key function in cholesterol processing." (PMID 38348876, 2024). "Atherosclerosis in apolipoprotein E-deficient (Apoe−/−) mice vaccinated with p18 (identical sequence in human and mouse) reduced atherosclerosis." (PMID 39211769, 2024). "In fact, Il18 gene deletion and the forced expression of the IL-18 binding protein, a natural inhibitor of IL-18, both decreased atherosclerosis in apolipoprotein E-deficient mice." (PMID 39451191, 2024). "In contrast, a potentially more conservative pharmacological approach using a Nox2-specific inhibitor slows the progression of atherosclerosis in mice haploinsufficient for the insulin receptor, and deficient in Apolipoprotein E." (PMID 39401163, 2024). "In contrast, in animal models of atherosclerosis, recombinant IL-27 administration inhibited the progression of atherosclerosis in ApoE-deficient mice." (PMID 38786961, 2024).
atherosclerosis (continued). "In the current study, the susceptibility to atherosclerosis in apoE KO rabbits is highlighted in the aorta and femoral artery but only mildly increased in the coronary arteries." (PMID 39087075, 2024). "Apolipoprotein-E (ApoE) is another molecule that has been linked to AD, atherosclerosis, and other inflammatory conditions." (PMID 38255891, 2024). "We first demonstrated that LXN expression is increased and colocalizes with macrophages in both human and murine atherosclerotic lesions, and that LXN deficiency decreases atherosclerosis in ApoE-/- mice." (PMID 39424784, 2024). "In animal models, APOE-deficient mice have increased microvascular and endocardial damage, along with a faster progression of atherosclerosis compared with WT mice." (PMID 39571156, 2024). "In mice, the most applied atherosclerosis models were Apolipoprotein E-deficient (ApoE-/-) mice on high-fat diet, although also C57BL/6J wild-type mice on long-term high-fat diet as model of metabolic disturbance have been studied." (PMID 39717783, 2024). "On the other hand, deletion of Scrib in ApoE-deficient mice impairs vascular permeability and promotes atherosclerosis development, indicating that SCRIB contributes to anti-inflammatory responses in endothelial cells." (PMID 37583551, 2023). "ApoE-deficient (Apoe−/−) mice enable the study of the similarities between atherosclerosis models and human pathology and diet." (PMID 38139244, 2023). "The present study assessed the metabolic and atheroprotective effects of intermittent fasting intervention (IF) in atherosclerosis-prone apolipoprotein E-deficient (Apoe-/-) mice." (PMID 36831200, 2023). "For example, both chronic administration and genetic deficiency of IL-6 have been reported to worsen atherosclerosis in ApoE knockout mice." (PMID 37018396, 2023). "Consistent with this, Akkermansia supplementation reduced inflammation-induced damage and atherosclerosis in the hearts of Apolipoprotein E deficient mice fed a Western Diet." (PMID 37759673, 2023). "The apolipoprotein E-deficient (ApoE−/−) mouse is a widely used animal model of atherosclerosis, demonstrating spontaneous atherosclerotic lesions throughout the aortic tree and late aortic valve sclerosis similar to that observed in humans." (PMID 37762794, 2023). "The apoE gene has been identified as a genetic risk factor for atherosclerosis, cardiovascular diseases, and Alzheimer’s disease (AD)." (PMID 36830968, 2023). "To investigate the effect of GV1001 on ligature-induced periodontitis and atherosclerosis, we used both WT and ApoE-deficient mice." (PMID 37628753, 2023). "In vivo experiments confirmed that dabigatran attenuates atherosclerosis in ApoE deficiency mice and protects against high-fat diet-induced fatty liver disease in mice." (PMID 37046189, 2023). "Employing Gsdme- and apolipoprotein E-deficient (Gsdme−/−/ApoE−/−) and ApoE−/− mice, an atherosclerosis model was created on a Western diet (WD)." (PMID 37761020, 2023). "Animal studies have also shown that overexpression of VEGFA increases the likelihood of atherosclerosis in ApoE-deficient mice." (PMID 38089766, 2023). "AMPK activation was also shown to prevent the development of long-term atherosclerosis in ApoE-deficient mice by reducing the number of atheromata macrophages, as well as enhancing the anti-atherogenic effects of HDLs." (PMID 36586434, 2023). "Atherosclerosis-prone apolipoprotein E-deficient (ApoE−/−) mouse model is a valuable tool for studying the development of atherosclerotic plaques." (PMID 37210385, 2023).